ROS1 (ROS proto-oncogene 1, receptor tyrosine kinase)
Diseases named in the same sentence as ROS1 in open-access papers (continued):
Sharing a sentence is not in itself a finding about the gene and the disease.
adenocarcinoma (continued). "All patients were untreated before enrollment and had histologically confirmed adenocarcinoma without sensitizing EGFR/ALK/ROS1 alterations." (PMID 34724131, 2022). "Consistent with previous observations, chromosomal rearrangements involving ROS1 in our cohort were mostly identified from younger patients with a median of 52 years old, females (63–66%), never smokers (75–76%), and with adenocarcinoma histology (97–98%)." (PMID 34511132, 2021). "The clinical characteristics of ROS1- and ALK-rearranged NSCLCs are quite similar: Both rearrangements are more common in younger, never- or light-smoker patients with a histologic diagnosis of adenocarcinoma." (PMID 34884672, 2021). "Our data showed that ALK, ROS1, BRAF or KRAS gene alterations were significantly more frequent in adenocarcinomas with a mucus‐producing component or micropapillary component, and these two components could be a nonpredominant component in some cases." (PMID 32729257, 2020). "Similar to the findings of previous studies, we found that ROS1 gene fusions occurred predominately in younger patients, women, and patients with adenocarcinoma without smoking history." (PMID 32168429, 2020). "Similar to ALK-rearranged adenocarcinomas, an intracellular mucin vacuole is frequently observed in ROS1-rearranged adenocarcinomas; therefore, inadequate immunostaining should not be missed." (PMID 29538329, 2018). "Among HER2-overexpressing adenocarcinomas, 1 (16.7%) and 2 (33.3%) had EGFR and KRAS mutations, respectively, while none had ALK or ROS1 rearrangements." (PMID 28146588, 2017). "Most of the ROS1 rearrangements were detected in adenocarcinoma (14/15) but no enrichment in a particular histological subtype was demonstrated." (PMID 28881815, 2017). "ROS1 rearrangements are more commonly found in never or mild smokers patients with adenocarcinoma (ADC) histology and in triple negative (EGFR/KRAS/ALK) population, similar to patients with ALK-rearranged NSCLC." (PMID 26783962, 2016). "Similar to ALK fusions, ROS1 rearrangement-positive patients had tendencies to be younger, never-smoker, and with adenocarcinoma histology." (PMID 27738334, 2016). "Patients harboring ROS1 rearrangement were mostly young (8/10), females (7/10) and non-smokers (7/10) with adenocarcinoma (10/10) and acinar pattern." (PMID 27488371, 2016). "VAMP2-NRG1 was reported in a 67-year-old never-smoker woman with adenocarcinoma with no mutation in EGFR, KRAS and BRAF and with no fusion genes involving ALK, ROS1 or RET." (PMID 27626312, 2016). "Patients with ROS1 rearrangements were significantly younger and more likely to be never smokers and all of the ROS1-positive tumors were adenocarcinomas with a tendency toward higher grade." (PMID 22928112, 2012). "Other examples of carcinogenic drivers for adenocarcinoma include modifications in protein kinase B (AKT), BRAF, human epidermal growth factor receptor-2 (HER2), phosphatidylinositol-4,5-bisphosphate 3-kinase catalytic subunit alpha (PIK3CA), MET, ROS1, RET, and KRAS." (PMID 35004079, 2022). "Seventeen studies aimed at predicting EGFR status, one aimed at predicting ALK status, three at predicting both EGFR and KRAS status, one at identifying ALK/ROS1/RET fusion-positive versus fusion-negative adenocarcinomas and two at predicting the PD-L1 expression level." (PMID 32486314, 2020). "In our investigated cohort of triple-negative NSCLCs (EGFR, KRAS, and BRAF mutation negative) the number of cases with either ROS1 or RET fusions were similar to that of ALK-positive cases, supporting the need of multiplexed gene fusion diagnostics in NSCLC and adenocarcinoma specifically." (PMID 28415793, 2017). "Young, female, and non-smoking patients with adenocarcinoma and without other RTKs aberrance should undergo tests for ROS1 rearrangement because patients with these characteristics may carry ROS1 rearrangement." (PMID 27488371, 2016).
adenocarcinoma (continued). "For adenocarcinoma specifically, DM was observed in promoters [hypermethylated RASL12; SPTAN1, mir-26a, hypomethylated NQO1, SIRPB1, NF1A] and gene bodies [hypermethylated AKAP13, ANK family, PRKCE, ROS1; hypomethylated FAM171A1, PARK2, BCAS3, RHOJ] and many others." (PMID 26683690, 2015). "Previous studies showed that the clinical characteristics of ROS1-fusion positive patients were the young, the nonsmoker, and the adenocarcinoma patients who might benefit most from targeted therapy." (PMID 25905642, 2015). "In a large cohort of 1478 NSCLCs, ROS1 expression was correlated with better survival and specific features such as low T stages, TTF1 and napsin expression, and certain histomorphological adenocarcinoma patterns (lepidic, acinar, and solid), although there is also a contradictory data." (PMID 26475437, 2015). "The median age of ROS1-fusion positive patients was younger than ROS1-fusion negative cases in the limited subsets (55 vs 58 years), suggesting that ROS1 rearrangement in resected stage IIIA-N2 NSCLC occurred mainly in certain subgroups, such as the young and those with adenocarcinoma." (PMID 25905642, 2015). "The growing number of detected tyrosine kinase fusions in predominantly EGFRwt/KRASwt adenocarcinomas (including ALK, RET, and ROS1) are also becoming increasingly important in the therapeutic setting, as these alterations are/may become targets for specialized molecular agents." (PMID 24205279, 2013). "ROS1 rearrangements are found in 0.9–2.6% of NSCLC cases, and patients with ROS1-positive NSCLC tend to be younger, never-smokers, and diagnosed with adenocarcinoma." (PMID 38705930, 2024). "ALK, ROS1, and RET rearrangement is typically more common among younger individuals, non-smokers, and light smokers who have been diagnosed with adenocarcinoma." (PMID 39685930, 2024). "In total, 52 patients were included [median age 57 years (range 32–81), 54% female, 62% never smokers, 98% adenocarcinoma]; 71% and 29% were ALK- and ROS1-positive, respectively." (PMID 33613692, 2021). "Fusions involving the rearranged during transfection proto-oncogene (RET) occur in 1–2% of NSCLC, and are more commonly seen in patients with minimal to no smoking history and adenocarcinoma histologic subtype, reminiscent of ALK and ROS1 fusions." (PMID 32183422, 2020). "Biopsy of the right supraclavicular lymph node revealed lung tissue adenocarcinoma and negative Kirsten rat sarcoma viral oncogene homolog (K-Ras), epidermal growth factor receptor (EGFR), B-raf proto-oncogene (BRAF), C-ros oncogene 1 (ROS1), and anaplastic lymphoma kinase (ALK) rearrangement." (PMID 33728131, 2021).
CNS tumors (10 papers, 2011 to 2025). "Six different ROS1 fusion partners have already been described in pediatric CNS tumors (+/−7% of pediatric CNS tumors): GOPC, ARCN1, CHCHD3, ZCCHC8, TPR and CEP85L." (PMID 39409964, 2024). "Furthermore, entrectinib unlike other TKI can sustain prolonged CNS exposure making it a suitable drug for treating ROS1 positive primary CNS tumors." (PMID 35169893, 2022). "Moreover, Entrectinib, a potent CNS-penetrant inhibitor of TRKA/B/C, ROS1 and ALK, was also evaluated to treat children and young adults with solid or primary CNS tumors harboring NTRK, ROS1 or ALK aberrations." (PMID 36839989, 2023). "Entrectinib (RXDX-101), a TRKA/B/C, ROS1, and ALK inhibitor, is being studied in a phase I/II trial (NCT02650401) recruiting children and young adults with recurrent/refractory CNS tumors harboring NTRK1/2/3, ROS1, and ALK molecular alterations, as confirmed by a CLIA-approved lab." (PMID 31970590, 2020). "In pediatric CNS neoplasms these 72 kinase fusions appear as 118 unique fusion–entity pairs, mainly in glial entities (97%; 114/118), except for some NTRK- (2%; 2/118), ALK- (1%; 1/118) and ROS1- (1%; 1/118) fusions that have been identified in non-glial tumors." (PMID 35169893, 2022).
infection (8 papers, 2016 to 2024). The state of being infected such as from the introduction of a foreign agent such as serum, vaccine, antigenic substance or organism. "Infection experiments in maize seedlings showed that ros1 mutants cause significantly fewer dead plants compared to the wild type." (PMID 27332891, 2016). "Compared to wild type infections and infections with ros1 deletion strains the strains expressing ros1 prematurely caused severely attenuated disease symptoms ranging from chlorosis to very small tumors." (PMID 27332891, 2016). "To confirm a functional role of DNA methylation/demethylation in galls, we performed infection tests in Arabidopsis mutant lines in which methyltransferase and DNA demethylase ROS1 activities were compromised." (PMID 35872574, 2022). "We found a significant decrease in the infection rates in the DNA methyltransferase mutants (cmt3, drm1/drm2, ddc and met1) and in the DNA demethylase ros1 mutant compared to the Col‐0 wild‐type control (P < 0.05)." (PMID 35872574, 2022). "Consistent with previous reports using the ros1 DNA demethylase single mutant, At4G11170 showed higher expression in the rdd mutant following infection." (PMID 28894455, 2017). "Among the upregulated genes in wild type infections are 38 putative transcription factors which are Ros1-regulated." (PMID 27332891, 2016). "In particular, only 4.8% of the plants infected with the ros1 mutant mixture were dead after 12 days compared to 53.7% for the FB1 x FB2 infection." (PMID 27332891, 2016). "ros1 was expressed at a very low basal level in axenic culture and during the early steps of maize infection." (PMID 27332891, 2016). "Four of them (UMAG_03138, UMAG_05926, UMAG_03046, UMAG_12258) exhibited a 50-fold higher expression in infections with wild type compared to the ros1 mutant strains." (PMID 27332891, 2016). "However, during late stages of infection Ros1 is essential for fungal karyogamy, massive proliferation of diploid fungal cells and spore formation." (PMID 27332891, 2016). "ros1 deletion strains are locked in the dikaryotic, filamentous stage of infection." (PMID 27332891, 2016). "To determine at which stage of development ros1 deletion strains are affected, we stained fungal hyphae with wheat germ agglutinin-Alexa Fluor 488 and followed the sequence of events leading to the formation of mature teliospores in wild-type infections by confocal microscopy." (PMID 27332891, 2016). "The DNA demethylase genes ROS1, DME, and DML3 were downregulated in the syncytia during early and/or late infection stages." (PMID 36704169, 2022). "RMG1 is a primary target of RNA‐directed DNA methylation (RdDM), and its expression is controlled by pathogen‐induced Repressor of Silencing 1 (ROS1), which can suppress the RdDM activity and therefore ensure proper expression of the RMG1 in response to infection by the pathogen P. syringae pv." (PMID 38460112, 2024). "Until 4 days after infection, growth of the ros1 deletion strains was indistinguishable from the growth of wild type strains." (PMID 27332891, 2016).
lung (4 papers, 2019 to 2026). "Overall survival (OS) for Stage IV lung ADC at initial diagnosis were analyzed in patients with BRAF V600E or with undetected mutation (no driver mutation/fusion detected in BRAF, EGFR, KRAS, ALK, ROS1, RET, HER2, or MET genes)." (PMID 31234388, 2019).
hematologic malignancies (2 papers, 2021 to 2024). "We found that high expression of SEC61A1 was associated with upregulation of EPHA3, MMP7, BIRC7, and ROS1, all of which have been reported as prognostic markers or therapeutic targets in hematological malignancies." (PMID 38584833, 2024).
epithelial neoplasm (1 paper, 2023). A benign or malignant neoplasm that arises from and is composed of epithelial cells. "TFG is a well-known fusion partner in a variety of mesenchymal and epithelial neoplasms of different organs, mostly fused to other receptor tyrosine kinases such as ALK, ROS1, and NTRK." (PMID 36690805, 2023).
nervous system disorder (1 paper, 2025). A non-neoplastic or neoplastic disorder that affects the brain, spinal cord, or peripheral nerves. "To explore the neurotoxicity profiles of ROS1 inhibitors, we analyzed the occurrence and reporting odds ratios (RORs) for “Nervous system disorders” at the SOC level." (PMID 41586108, 2025).
psychiatric disorder (1 paper, 2021). A disorder characterized by behavioral and/or psychological abnormalities, often accompanied by physical symptoms. "It is noteworthy, that two of five patients with AE-related treatment cessation were discontinued due to psychiatric disorders, effects that have not been reported for other ALK or ROS1-TKIs." (PMID 33613692, 2021).
ROS1 also shares sentences with these, for which no sentence is quoted: large cell carcinoma (4 papers); triple-negative breast carcinoma (4); cutaneous melanoma (3); liposarcoma (3); non-Hodgkin lymphoma (3); Spitz nevi (3); anaplastic astrocytoma (2); asthma (2); breast invasive ductal carcinoma (2); epithelioid hemangioendothelioma (2); glioneuronal tumors (2); hepatic angiosarcoma (2); hepatocellular adenocarcinoma (2); interstitial lung disease (2); leiomyosarcoma (2); lymphangitis (2); malignant pleural mesothelioma (2); medullary thyroid cancer (2); metastatic colorectal cancer (2); myocardial infarction (2); neuroendocrine carcinoma (2); pancreatic adenocarcinoma (2); small cell carcinoma (2); soft tissue tumor (2); synovial sarcoma (2); thoracic tumors (2); undifferentiated pleomorphic sarcoma (2); vulvar carcinoma (2); acute lymphoblastic leukemia (1); acute megakaryoblastic leukemia (1).
A further 86 diseases each share a sentence with ROS1 in 1 paper.